CDNF (cerebral dopamine neurotrophic factor)
Description:
Trophic factor for dopamine neurons. Prevents the 6-hydroxydopamine (6-OHDA)-induced degeneration of dopaminergic neurons. When administered after 6-OHDA-lesioning, restores the dopaminergic function and prevents the degeneration of dopaminergic neurons in substantia nigra (By similarity).
Synonyms: ARMETL1
Tractability: Antibody: UniProt places it where antibodies can reach, with high confidence; UniProt predicts a signal peptide or a membrane-spanning region; its Gene Ontology location is reachable by antibodies, with medium confidence.
Gene: Protein-coding gene on chromosome 10 (14,818,270 to 14,838,575, reverse strand). Ensembl gene ENSG00000185267.
Subcellular location: Secreted
Gene Ontology:
Molecular function: growth factor activity
Biological process: dopaminergic neuron differentiation; neuron projection development; signal transduction
Cellular component: extracellular region
Genetic constraint (gnomAD): Loss-of-function variants: 8 observed, 10.82 expected, observed/expected ratio (o/e) 0.74, 90% interval 0.43 to 1.33. The upper end of that interval is the gene's LOEUF score, 1.33, which puts it in group 5 of 6, group 1 being the genes least tolerant of losing a copy. Missense variants: 216 observed, 203.53 expected, observed/expected ratio (o/e) 1.06, 90% interval 0.95 to 1.19. Synonymous variants: 81 observed, 78.38 expected, observed/expected ratio (o/e) 1.03, 90% interval 0.86 to 1.24.
Homologues: Orthologues: chimpanzee CDNF (99% identical), dog CDNF (88% identical), rabbit CDNF (87% identical), guinea pig CDNF (83% identical), mouse Cdnf (78% identical), rat Cdnf (73% identical), macaque CDNF (65% identical), tropical clawed frog cdnf (54% identical), zebrafish cdnf (47% identical), Drosophila melanogaster Manf (43% identical), Caenorhabditis elegans manf-1 (39% identical). Paralogues in human: MANF (56% identical).
Diseases named in the same sentence as CDNF in open-access papers:
CDNF is named in the same sentence as 40 diseases in open-access papers, as found by Europe PMC text mining. Sharing a sentence is not in itself a finding about the gene and the disease. The quoted sentences say what the papers report.
Parkinson disease (37 papers, 2013 to 2025). A progressive degenerative disorder of the central nervous system characterized by loss of dopamine producing neurons in the substantia nigra and the presence of Lewy bodies in the substantia nigra and locus coeruleus. "Notably, ER stress has been implicated in several neurodegenerative diseases, including Parkinson's disease, positioning CDNF as a promising therapeutic candidate." (PMID 40827505, 2025). "CDNF is currently being tested in clinical trials as atreatment for Parkinson’s disease (PD) (Lindholm, Saarma,2022), as it is able to slow down the degeneration of DA neurons." (PMID 39027124, 2024). "CDNF is a neurotrophic factor that has recently been tested in combined phase I/II clinical trials for the treatment of Parkinson’s disease—a progressive neurodegenerative disorder characterized by the loss of midbrain dopamine neurons." (PMID 36012764, 2022). "In rodent Parkinson’s disease models, CDNF and MANF have been shown to promote the survival of dopamine neurons." (PMID 35129674, 2022). "Although CDNF has been tested in phase I-II clinical trials in Parkinson’s disease patients, the molecular mechanism of its action is still under investigation." (PMID 36012764, 2022). "A minimal clinical important difference in Unified Parkinson’s Disease Rating Scale (UPDRS III) (off) was observed in the CDNF dose-groups suggesting a potential slowing of disease progression." (PMID 34907395, 2022). "Airavaara, Almeida, and colleagues show that CDNF, a therapeutic protein that is in clinical trials for Parkinson’s disease, interacts with α-synuclein." (PMID 33940158, 2021). "Their great therapeutic potential has led to ongoing phase 1/2 clinical trial of CDNF in Parkinson’s disease (ClinicalTrials.gov: NCT03295786)." (PMID 34575854, 2021). "Research has shown that, in a rat model of Parkinson's disease, neuronal CDNF and MANF protect dopaminergic neurons and support nerve repair." (PMID 32508943, 2020). "There has been great interest due to their success in animal models of Parkinson’s disease and stroke; and CDNF is currently in clinical trials for Parkinson’s disease." (PMID 31044581, 2019). "Exogenous MANF and CDNF possess therapeutic properties in several neurological disease models, including Parkinson’s disease and stroke." (PMID 31044581, 2019). "While MANF has been effective in cells and some animal models, CDNF has shown efficacy in rodent models of the disease, and CDNF is currently in Phase I/II clinical trials for Parkinson’s disease." (PMID 31044581, 2019). "Previously, neurorestorative efficacy of CDNF in the 6-hydroxydopamine (6-OHDA) model of Parkinson’s disease as well as diffusion of the protein in the striatum (STR) has been demonstrated and studied." (PMID 31244598, 2019). "CDNF has been studied extensively for Parkinson’s disease since the initial study showed it to be neuroprotective in a 6-OHDA model." (PMID 31044581, 2019). "Subsequently, neuroprotective and neurorestorative studies of CDNF were performed in a 6-OHDA rat model or a mouse MPTP model of Parkinson’s disease." (PMID 29966219, 2018). "The neuroprotective effect of CDNF was first identified in a 6-OHDA rat model of Parkinson’s disease." (PMID 29966219, 2018). "Most importantly, MANF and especially CDNF are neurorestorative in the animal models of Parkinson’s disease." (PMID 30234112, 2018). "Cerebral dopamine neurotrophic factor (CDNF) protects the nigrostriatal dopaminergic (DA) neurons in rodent models of Parkinson’s disease and restores DA circuitry when delivered after these neurons have begun to degenerate." (PMID 28275710, 2017). "We demonstrate for the first time a therapeutic effect of CDNF in a unilateral 6-hydroxydopamine (6-OHDA) lesion model of Parkinson’s disease in marmoset monkeys." (PMID 26901822, 2016).
Parkinson disease (continued). "It is reported that CDNF also showed a cytoprotective effect on 6-OHDA-induced Parkinson’s disease model rats, and that the expression level of CDNF mRNA was constitutive and uninfluenced by ER stress." (PMID 26820513, 2016). "The neuroprotective effect of CDNF has previously been demonstrated in rat experimental models of Parkinson’s disease." (PMID 25343619, 2014). "Results from this study provide additional evidence that CDNF can be considered a potential treatment of Parkinson's disease." (PMID 23532969, 2013). "Recombinant human MANF (HsMANF) and CDNF (HsCDNF) protect and repair midbrain dopaminergic (DA) neurons in rodent models of Parkinson’s disease in vivo." (PMID 24019940, 2013). "CDNF has also been tested in Phase I clinical trials in Parkinson’s disease patients." (PMID 40783454, 2025). "Summary of studies examining the effect of CDNF in the rodent models of Parkinson’s disease." (PMID 37555005, 2023). "Both MANF and CDNF have positive effects on models of Parkinson’s disease, however, to determine whether this is through an ER-related mechanism needs further study." (PMID 31044581, 2019). "Both MANF and CDNF have mainly been used in models of Parkinson’s disease." (PMID 31044581, 2019). "Results from the current clinical trial with CDNF in Parkinson’s disease may provide more information for future potential therapies." (PMID 31044581, 2019). "In addition to CDNF protein alone, a few studies have used AAV-CDNF in a 6-OHDA model of Parkinson’s disease in rats." (PMID 31044581, 2019). "CDNF has been shown to protect and repair the dopaminergic system in rat models of Parkinson’s disease (PD), which is characterized by degeneration of dopaminergic neurons; it may thus have therapeutic benefits." (PMID 29298719, 2018). "When injected into the brain, recombinant mammalian MANF (Mesencephalic Astrocyte-derived Neurotrophic Factor) and CDNF (Cerebral Dopamine Neurotrophic Factor) protect and repair dopaminergic neurons in toxin-induced rodent models of Parkinson’s disease (PD) in vivo." (PMID 26975047, 2016). "Our results show the anti-inflammatory effect of CDNF in a 6-OHDA rat of Parkinson’s disease." (PMID 25511018, 2014). "This indicated that CDNF could have a protective effect in toxin models of Parkinson’s disease." (PMID 31044581, 2019). "However, currently only CDNF is at the trial stage and only for Parkinson’s disease." (PMID 31044581, 2019). "However, it remains unknown whether CDNF is able to revert from neuroinflammation in vivo and in an animal model of Parkinson’s disease (PD)." (PMID 25511018, 2014). "Furthermore, CDNF's dual neurotrophic and neuroprotective roles in both the central and PNSs position it as an ideal candidate for a wide range of clinical applications, including the treatment of Parkinson's disease, peripheral neuropathies, and chronic pain syndromes." (PMID 40827505, 2025). "In this study, we investigated the effects of M1 and M7 on the protective activity of CDNF in PC12 cells, which were treated with 6-hydroxydopamine (6-OHDA) to mimic Parkinson's disease." (PMID 37815547, 2023). "Cerebral dopamine neurotrophic factor (CDNF) is a neurotrophic factor that has beneficial effects on dopamine neurons in both in vitro and in vivo models of Parkinson’s disease (PD)." (PMID 36012764, 2022). "CDNF and MANF have cytoprotective effects in different animal disease models, such as Parkinson’s disease, ischemic stroke, and spinocerebellar ataxia." (PMID 35129674, 2022). "MANF and its homolog, the cerebral dopamine neurotrophic factor (CDNF), have been identified to protect and rescue midbrain dopaminergic neurons in the rat 6-OHDA model of Parkinson’s disease." (PMID 30760285, 2019). "Namely these neurons degenerate in the Parkinson’s disease and are rescued by MANF and CDNF in the animal experiments." (PMID 30234112, 2018).
Parkinson disease (continued). "Previous studies reported that CDNF and MANF have protective functions toward the midbrain dopaminergic system in models of Parkinson’s disease and toward cortical neurons in models of ischemia." (PMID 25343619, 2014). "Cerebral dopamine neurotrophic factor (CDNF) protein has been shown to protect the nigrostriatal dopaminergic pathway when given as intrastriatal infusions in rat and mouse models of Parkinson's disease (PD)." (PMID 23532969, 2013). "Notably, both CDNF and MANF display neuroprotective effects that extend beyond Parkinson’s disease, embracing conditions like cerebral ischemia and spinocerebellar ataxia." (PMID 37751132, 2023). "CDNF was also tested using a mouse model treated with toxin MPTP (1-methyl-4-phenyl-1,2,5,6-tetrahydropyridine), a neurotoxin that has been shown to result in parkinsonism in humans." (PMID 31044581, 2019). "The anti-inflammatory effect of the cerebral dopamine neurotrophic factor (CDNF) was shown recently in primary glial cell cultures, yet such effect remains unknown both in vivo and in 6-hydroxydopamine (6-OHDA) models of Parkinson’s disease (PD)." (PMID 25511018, 2014). "Recombinant CDNF protein has been shown to reduce levels of the Atf6 UPR transcript in thapsigargin-treated embryonic mouse dopamine neurons in vitro and the level of GRP78 protein and ATF6 transcripts in the rat striatum in a 6-OHDA model of Parkinson’s disease in vivo." (PMID 36012764, 2022). "Therefore, CDNF and MANF have been hypothesized to be survival factors for dopamine neurons, which degenerate in Parkinson’s disease and hence lead to the characteristic motor symptoms." (PMID 35129674, 2022). "Cerebral dopamine neurotrophic factor (CDNF), a paralog of mesencephalic astrocyte-derived neurotrophic factor (MANF), was first characterized in 2007 as a trophic factor for midbrain dopamine neurons in a rat 6-hydroxydopamine (6-OHDA) model of Parkinson’s disease." (PMID 36012764, 2022). "CDNF, a trophic factor for dopamine neurons that prevents the 6-hydroxydopamine (6-OHDA)-induced degeneration of dopaminergic neurons in substantia nigra may have a role in the evolution of Parkinson’s disease." (PMID 33218114, 2020). "Glial cell line-derived neurotrophic factor (GDNF), cerebral dopamine neurotrophic factor (CDNF), and mesencephalic astrocyte-derived neurotrophic factor (MANF) have shown neuroprotective and restorative effects on nigral dopaminergic neurons in various animal models of Parkinson’s disease." (PMID 29349573, 2018). "CDNF protects and restores the function of dopamine (DA) neurons in rodent and non-human primate (NHP) toxin models of Parkinson’s disease (PD) and therefore shows promise as a drug candidate for disease-modifying treatment of PD." (PMID 39019902, 2024). "Cerebral dopamine neurotrophic factor (CDNF) has shown therapeutic potential in rodent and non-human primate models of Parkinson’s disease by protecting the dopamine neurons from degeneration and even restoring their phenotype and function." (PMID 31244598, 2019). "CDNF [cerebral dopamine neurotrophic factor (NTF)] and GDNF (glial cell line-derived NTF) have shown neuroprotective and neurorestorative effects in rodent and nonhuman primate models of Parkinson’s disease (PD)." (PMID 28303260, 2017). "Cerebral dopamine neurotrophic factor (CDNF) is a novel endoplasmic reticulum located protein with neurotrophic factor properties that protects and restores dopamine neurons in rodent and non-human primate models of Parkinson’s disease." (PMID 36807563, 2023).
Stroke (10 papers, 2018 to 2024). Sudden impairment of blood flow to a part of the brain due to occlusion or rupture of an artery to the brain. "Further studies exploring the mechanisms underlying the effects of CDNF on stroke may lead to a better understanding of the potential for therapies." (PMID 29966219, 2018). "In our study, PRP obtained from stroke patients exhibited lower CDNF levels, while concurrently displaying an increased expression of GPVI and higher aggregation in response to collagen." (PMID 39256999, 2024). "In rat cortical stroke model, subcutaneous (s.c.)delivery of CDNF was shown to suppress stroke-induced platelet activation, aggregation responses, and subsequent neuroinflammation." (PMID 39256999, 2024). "To address these concerns, we designed a series of experiments to investigate the effects of CDNF on platelet activity, lipid mediator biosynthesis, and neuroinflammatory responses in stroke patients and rats." (PMID 39256999, 2024). "While added CDNF exhibited no discernible effect on the aggregation responses of PRP induced by ADP or TRAP-6, the presence of 0.1 μg/mL of CDNF downregulated collagen-induced aggregation responses of PRP from stroke patients." (PMID 39256999, 2024). "In conclusion, we discovered that CDNF functions as a hamper of platelet activation, aggregation, and the ensuing thrombo-inflammation that typically follows a stroke insult." (PMID 39256999, 2024). "In summary, our study highlights CDNF as a promising therapeutic target for mitigating platelet-induced inflammation and enhancing recovery in stroke." (PMID 39256999, 2024). "There are several reports, showing alterations in levels of circulating MANF/CDNF in patients with diabetes, autoimmune diseases (rheumatoid arthritis and systemic lupus erythematosus), PD and stroke." (PMID 34575854, 2021). "Notably, CDNF treatment not only reduced TXB2 production in platelets but also normalized the levels of stroke-upregulated COX, 12-lipoxygenase (LOX), and CYP450-derived oxylipins to baseline levels." (PMID 39256999, 2024). "Indeed, externally added CDNF was shown to effectively mitigate collagen- or AA-induced aggregation in PRP derived from stroke patients." (PMID 39256999, 2024). "Notably, the addition of CDNF at either 0.1 or 1 μg/mL significantly mitigated AA-induced aggregation responses of PRP derived from stroke patients compared with the PBS group." (PMID 39256999, 2024). "The administration of recombinant forms of cerebral dopamine neurotrophic factor (CDNF) or MANF post-stroke has been shown to enhance recovery of neurological function, presenting a promising therapeutic strategy for addressing stroke-induced limb dysfunctions." (PMID 38377025, 2024). "Since higher aggregation responses along with lower CDNF levels in PRP were found in the stroke group, we sought to investigate whether exogenous CDNF supplementation could potentially regulate PRP aggregation responses." (PMID 39256999, 2024). "In addition, the co-culture of BV2 microglial cells with CDNF-treated platelets from stroke patients exhibited reduced polarization toward a pro-inflammatory phenotype." (PMID 39256999, 2024). "Besides, upregulation of Mesencephalic Astrocyte-Derived Neurotrophic Factor (MANF) and Cerebral Dopamine Neurotrophic Factor (CDNF) in astrocytes was observed in the experimental model of stroke, which alleviates the damage of endoplasmic reticulum stress." (PMID 34867201, 2021). "In addition, on days 7 and 14 post-stroke CDNF post-treatment decreased both the body asymmetry and Bederson’s score compared with the vehicle-treated group, suggesting that CDNF could accelerate neurofunctional recovery after ischemic stroke." (PMID 39256999, 2024). "Harnessing the CDNF pathway may offer a novel therapeutic strategy for stroke intervention." (PMID 39256999, 2024). "Therefore, CDNF may be a potential novel agent for neuroprotective and neuroinflammatory treatments for stroke." (PMID 29966219, 2018).
Stroke (continued). "In our previous study, MANF, a paralogous protein of CDNF, was shown to increase the density of ARG1+ and CD68+ cells in subcortical regions after stroke." (PMID 36792604, 2023). "Next, to investigate whether extracellularly added CDNF could mitigate platelet-induced pro-inflammatory responses in BV2 microglia, CDNF (1 μg/mL) was administered in the co-culture of BV2 microglial cells and platelets derived from stroke patients." (PMID 39256999, 2024). "Conversely, when BV2 microglial cells have already interacted with platelets from stroke patients, CDNF treatment fails to reverse the pro-inflammatory polarization of these BV2 microglial cells." (PMID 39256999, 2024). "Nevertheless, CDNF treatment did not affect the upregulated expression of iNOS or COX-2 in the BV2 cells co-cultured with platelets derived from stroke patients." (PMID 39256999, 2024). "Furthermore, for non-classical neurotrophic factors, mesencephalic astrocyte-derived neurotrophic factor (MANF), together with its homolog cerebral dopamine neurotrophic factor (CDNF), can promote the migration of neural progenitor cells in the stroke model." (PMID 35628525, 2022).